MELK (maternal embryonic leucine zipper kinase)
Diseases named in the same sentence as MELK in open-access papers (continued):
Sharing a sentence is not in itself a finding about the gene and the disease.
tumor (continued). "Finally, we sought to determine whether MELK was required for tumor formation in vivo." (PMID 29417930, 2018). "About half of the rare MELK‐positive non‐neoplastic cases displayed exclusively nuclear staining; in contrast, MELK staining in PIN and tumour samples was either exclusively cytoplasmic or both cytoplasmic and nuclear, but rarely exclusively nuclear." (PMID 29437778, 2018). "The small molecule MELK inhibitor, OTSSP167 potently inhibit NB tumor growth, and reprents a promising therapeutic strategy for high-risk NB." (PMID 29416794, 2018). "Sanguinarine shows efficacious anti-tumor effects through downregulating and dephosphorelating STRAP and MELK." (PMID 29783958, 2018). "The expression of MELK and downstream molecules was decreased in OTS167-treated xenograft tumor tissues, which revealed central necrosis and significant growth suppression." (PMID 26918358, 2016). "We have delineated roles of MELK in development/progression of SCLC and examined anti-tumor efficacy of OTS167, a highly potent MELK inhibitor, against SCLC." (PMID 26871945, 2016). "Since MELK was suggested to be one of key molecules that maintain characteristics of CSC, we explored the anti-tumor effect of OTS167 on the formation of LS as a preclinical model that recapitulates lung CSC." (PMID 26871945, 2016). "MELK is thought to bind and activate transcription factors c-JUN and FOXM1 and play a role in maintaining tumor initiating cells." (PMID 27574806, 2016). "Finally, we tested whether MELK can regulate tumor growth and peritoneal spreading and metastasis." (PMID 24885567, 2014). "In addition, MELK involvement in the inhibition of apoptosis may also promote tumor cell survival." (PMID 24167714, 2013). "In addition, MELK knockdown or downregulated EZH2 reduced the weight and volume of subcutaneous tumours of nude mice." (PMID 38652219, 2024). "Hence, MELK silencing downregulated EZH2 to inhibit LUAD cell proliferation and invasion and induce apoptosis, thereby suppressing tumour growth." (PMID 38652219, 2024). "Among the 991 BC tumor samples, GATA3 had the highest frequency of somatic SNVs, accounting for 13%; followed by FOXA1, accounting for 3%; AGR2, CA12, CEP55, CDC20, TBC1D9, and MELK had very few somatic SNVs." (PMID 39440050, 2024). "In addition, downregulation of MELK suppresses proliferation and survival of small cell lung cancer (SCLC) cells in vitro and tumour growth in vivo." (PMID 38652219, 2024). "Consistent with our speculation, an increased proportion of CD8+ tumor-infiltrating lymphocytes (TILs), especially granzyme A (GZMA)-positive cells, was detected in MELK knockdown tumors." (PMID 38970074, 2024). "This suggested that recovery of EIF4B and MELK phosphorylation represented a marker of proliferative tumor progression rather than a driver of resistance to AZD8055." (PMID 37642941, 2023). "After the detection of hub genes utilizing the PPI network of common upregulated genes, the top five hub genes, including AURKA, AURKB, KIF20A, MELK, and TTK that played the most critical role in both primary tumor cell and P7731 cell line, were selected to validate the study." (PMID 37231064, 2023). "Xenografts were established with MELK-overexpressing stable cells with or without elesclomol treatment, showing that elesclomol significantly reduced tumor volume and weight, which were increased by MELK overexpression." (PMID 37949877, 2023). "Of these, miR-485-3p, a tumor suppressor in GBM was presumed to inhibit MCM10 and MELK." (PMID 35109908, 2022). "qRT-PCR verified the higher MELK expression in NSCLC tumor samples than that in proximal normal tissues." (PMID 33931086, 2021). "Altogether, our work shows that MELK overexpressing cells are sensitive to the inhibition of HDAC4, which may provide novel intervention strategies to target tumor cells that overexpress MELK." (PMID 34550356, 2021).
tumor (continued). "Maternal embryonic leucine-zipper kinase (MELK) is a member of the Snf1/AMP-activated protein kinase (AMPK) family and is involved in cell cycle regulation, cell proliferation, apoptosis, and tumor formation." (PMID 33520717, 2020). "We detected that MELK overexpression could induce M2 macrophage polarization via the miR-34a/JAK2/STAT3 pathway, contributing to doxorubicin chemoresistance in the tumor microenvironment." (PMID 32391256, 2020). "Finally, ablation of MELK/EZH2/NF-κB axis can impair stemness of GSCs and promote differentiation, leading to a reduced tumor burden." (PMID 31380279, 2019). "Unlike other members of the AMPK family, MELK is not directly involved in the balance of cellular metabolism, but rather in cell cycle regulation, proliferation, apoptosis, and tumor formation." (PMID 31861475, 2019). "Zhang etal. reported that MELK might be an effective therapeutic target in CLL, and OTSSP167 exhibited potent anti-tumor activities in CLL cells." (PMID 31400751, 2019). "Across all clones tested, 23 of 34 injections with MELK-KO cells and 24 of 34 injections with Rosa26 cells resulted in detectable tumor formation, and no significant growth defect was observed in any MELK-KO clone." (PMID 29417930, 2018). "Both MELK and STRAP were significantly correlated with tumor stages." (PMID 29783958, 2018). "We were able to demonstrate increased levels of MELK protein in PIN lesions, medium‐stage and advanced‐stage tumours in the PB‐Cre/PtenloxP/loxP model, and in PIN, primary tumours and liver metastases in the PB‐Cre/p53loxP/loxPRbloxP/loxP model by immunohistochemistry (IHC) (Fig EV3B–D)." (PMID 29437778, 2018). "The results suggested that the high expression rate of MELK was not significantly correlated with the depth of tumor invasion in early stage (P > 0.05)." (PMID 30334367, 2018). "A recent CRISPR/Cas9 screen for essential genes involved in tumour growth revealed that the MELK protein known to be essential in tumour growth does not drive cell proliferation in cancer cells as previously thought." (PMID 30086710, 2018). "Comparing MELK expression from basal-like tumors (n = 1,144) with not basal-like tumor (n = 4,205), we confirm significantly increased MELK expression in the basal-like BC cohort (p<0.0001)." (PMID 28235006, 2017). "The tumor-specific MELK interaction with the JNK/c-JUN is likely one of the mechanisms for the selective apoptosis that occurs as a result of MELK inhibition in GBM stem cells, but not in normal progenitors." (PMID 26973435, 2016). "MELK was detected in all of the tumor tissues but not in any of the distal surgical margin samples, indicating that MELK is upregulated in GC tissues compared to normal stomach mucosa." (PMID 26701722, 2016). "Therefore, it should be important to consider NAT1 and MELK genes and their products as the targets in the therapeutic plans for LGG and HGG tumor separately." (PMID 26474389, 2015). "In particular, knockdown of MELK dramatically suppressed tumor growth in vivo, although the effect was not so significant in vitro." (PMID 24885567, 2014). "The positive rates of MELK protein detection were 37.7% (23/61) in non-tumor tissues and 65.4% (51/78) in tumor tissues, which is significant." (PMID 24885567, 2014). "Since MELK is selectively required for the survival of BBC cells, we sought to determine whether MELK also supports the oncogenic growth of BBC cells using both in vitro colony formation and in vivo xenograft tumor growth assays." (PMID 24844244, 2014).
tumor (continued). "Oral administration of 10 mg/kg OTSSP167 once a day for 14 days showed no tumor growth suppressive effect on PC-14 xenografts, further supporting the MELK-dependent antitumor activity of OTSSP167." (PMID 23283305, 2012). "UBE2C, CCNB1, CCNB2, PLOD2, NUP210, MELK, CDC20 genes were overexpressed in tumours and in CIN3/CIS relative to both Normal and CIN1/CIN2, suggesting that they could have a role to play in the early phase of tumorigenesis." (PMID 21338529, 2011). "UBE2C, CCNB1, CCNB2, PLOD2, NUP210, MELK, CDC20 were overexpressed in tumours and in CIN3/CIS relative to both Normal and CIN1/CIN2, suggesting that they could have an important role to play in the early phase of tumorigenesis." (PMID 21338529, 2011). "Notably, MELK and EIF4A1 were highly expressed in tumor cells." (PMID 40709174, 2025). "Moreover, the results obtained in the 3D BC model experiments suggest that MELK and ALK targeting could work also within the tumor and the tumor environment." (PMID 38589728, 2024). "In addition, there were significant negative correlations between MELK expression and tumor purity, and significant positive correlations between MELK expression and ESTIMATE score, immune score, and stromal score." (PMID 36353126, 2022). "Given that ectopic expression of MELK significantly enhanced the abilities of migration and invasion of KYSE70 and EC109 cells in vitro, we next investigate whether MELK promotes the lung metastasis of tumor cells in nude mice." (PMID 32047721, 2020). "We therefore hypothesized that MELK may promote EMT, a key step in tumor cell migration." (PMID 26701722, 2016). "Thus, the tumor-specific MELK interaction with JNK/c-JUN is likely one of the mechanisms for the selective apoptosis that occurs as a result of MELK inhibition in GSCs, but not in normal progenitors." (PMID 25852826, 2015). "To determine whether MELK is also important for BBC cells to grow as tumors in vivo, we transplanted BBC cells expressing inducible shMELK into the mammary fat pads of athymic mice to allow orthotopic tumor formation." (PMID 24844244, 2014). "Strikingly, all the four ER/PR+ tumor samples lacked detectable signal of MELK expression." (PMID 24844244, 2014). "Also, the impact of MELK on the tumor immune infiltration in HCC is still not evaluated." (PMID 35693941, 2022). "A clinicopathologic feature analysis revealed that MELK expression had no obvious correlation with age, FIGO stage, grade, and tumor size." (PMID 32391256, 2020). "Sorted cells expressed MELK, EZH2, and NF-κB in nuclei, however little signal was detected in the CD133− group representing non-GSC tumor cells (p < 0.01 and p < 0.001)." (PMID 31380279, 2019). "We found that, while the majority (~70%) of non‐neoplastic samples were negative for MELK expression, ~60% of PIN samples and more than 80% of tumour samples stained positively." (PMID 29437778, 2018). "Furthermore, the interaction between MELK/EZH2 complex and NF-κB preferentially occurs in GSCs compared with non-stem-like tumor cells." (PMID 31380279, 2019).
infection (6 papers, 2014 to 2025). The state of being infected such as from the introduction of a foreign agent such as serum, vaccine, antigenic substance or organism. "By screening a library of kinase inhibitors, we identified that OTS167, a pharmacological inhibitor of maternal embryonic leucine zipper kinase (MELK), strongly inhibits the infections caused by multiple influenza virus subtypes in cell culture." (PMID 40539108, 2025). "MELK, a serine/threonine kinase, has roles in cell proliferation and stress responses and is linked to immune modulation during infection." (PMID 41366310, 2025). "Infection of cells overexpressing MELK with wild-type HIV-1 resulted in premature CA disassembly and aberrant viral cDNA synthesis." (PMID 28683086, 2017). "To address this question, we combined lentiviral infection of MELK shRNA vector, to downregulate endogenous MELK protein, with overexpression of MELK wild type or the kinase dead version of MELK (MELK D150A)." (PMID 24739874, 2014). "Dysfunction of MELK could account for prolonged activation of the immune system post‐infection, contributing to a chronic inflammatory state, which may activate or maintain the sensitivity of nociceptors, setting off chronic pain." (PMID 39853911, 2025). "T119E and S146E mutants produced a little more late RT product than did the wild-type in MELK-KD cells and eventually failed to increase or retain this at 24 h post-infection, suggesting that these mutations promoted reverse transcription independently of MELK." (PMID 28683086, 2017). "Of note, MELK depletion did not significantly affect the amount of immediate early viral cDNA quantified at the R/U5 region 2 h post-infection, but profoundly reduced it thereafter by approximately 80% compared to Non-T." (PMID 28683086, 2017). "Importantly, MELK knockdown significantly impaired IAV PR/8 replication as shown by reduced viral NP protein levels and effectively inhibited the production of infectious viral particles into cell culture supernatant at 12 h post-infection." (PMID 40539108, 2025). "In contrast, viral cDNA synthesis after infection with HIV-1 bearing the S149E mutation was robustly restored, and even at an earlier time point than wild-type HIV-1 (approximately 1.7-fold increase compared to Non-T-wt, 8 h post-infection) (MELK-KD-2-S149E)." (PMID 28683086, 2017). "Knockdown of MELK mRNA expression following infection with a lentivirus expressing anti-MELK small hairpin RNA (shRNA) was confirmed by Western blotting; shRNA treatment also reduced, but did not eliminate, MELK protein expression." (PMID 26701722, 2016).
adenocarcinoma (1 paper, 2015). A common cancer characterized by the presence of malignant glandular cells. "Of the canonical changes noted, promoter (PR) DM loci with reciprocal changes in expression in adenocarcinomas included HBEGF, AGER, PTPRM, DPT, CST1, MELK; DM GB loci with concordant changes in expression included FOXM1, FERMT1, SLC7A5, and FAP genes." (PMID 26683690, 2015).
hematological malignancies (1 paper, 2014). "However, the expression and the function of MELK in hematological malignancies have not yet been characterized." (PMID 25365263, 2014).
MELK also shares sentences with these, for which no sentence is quoted: hematological cancers (4 papers); cervical adenocarcinoma (2); clear cell renal cell carcinoma (2); esophageal squamous cell carcinoma (2); non-small cell lung carcinoma (2); rectal cancer (2); squamous cell carcinoma (2); acute leukemia (1); asthma (1); atherosclerosis (1); B cell lymphomas (1); bacterial infection (1); benign pilocytic astrocytoma (1); bladder urothelial carcinoma (1); bone cancer (1); brain cancer (1); Cachexia (1); cervical diseases (1); cervical intraepithelial neoplasia (1); Cirrhosis (1); COVID-19 (1); dermatitis (1); diabetes (1); diffuse large B-cell lymphoma (1); Erythema (1); Fanconi anaemia (1); gallbladder carcinoma (1); head and neck cancer (1); head and neck squamous cell carcinoma (1); leiomyoma (1).
A further 14 diseases each share a sentence with MELK in 1 paper.